C3orf49 (chromosome 3 open reading frame 49)
Tractability: No criterion of Open Targets' tractability assessment is met for any kind of drug.
Gene: Protein-coding gene on chromosome 3 (63,819,299 to 63,848,636, forward strand). Ensembl gene ENSG00000163632.
Subcellular location (Human Protein Atlas): Cytosol; Centrosome; Vesicles
Homologues: Orthologues: chimpanzee C3H3orf49 (96% identical), macaque C2H3orf49 (95% identical), pig C3orf49 (76% identical), rabbit C3orf49 (76% identical), dog C3orf49 (75% identical), rat C15h3orf49 (66% identical), mouse Gm11100 (64% identical), tropical clawed frog c4h3orf49 (42% identical), Drosophila melanogaster CG11929 (16% identical).